CCL5 (C-C motif chemokine ligand 5)
Diseases named in the same sentence as CCL5 in open-access papers (continued):
Sharing a sentence is not in itself a finding about the gene and the disease.
osteosarcoma (continued). "CCL5-trigered migration in osteosarcoma cells was examined using the Transwell assay." (PMID 22506069, 2012). "Thus, CCL5 may serve as a biomarker for osteosarcoma prognosis, and may be a potential molecular target for osteosarcoma therapy." (PMID 32630699, 2020). "However, the effect of CCL5 on migration activity and integrin expression in human osteosarcoma cells is mostly unknown." (PMID 22506069, 2012). "Furthermore, the discovery of CCL5-mediated pathway helps us to understand the mechanism of human osteosarcoma metastasis and may help us to develop effective therapy in the future." (PMID 22506069, 2012). "Chemokines (CCL3 and CCL5) and other proangiogenic factors also upregulate VEGF and promote neovasculature in osteosarcoma, and high expression of VEGF and VEGFR2 is associated with poor prognosis." (PMID 37569894, 2023). "Bone marrow mesenchymal stem cells (MSCs) secrete cytokines, chemokine ligand 5 (CCL5), IL-6, and VEGF that promote growth, metastasis, and angiogenesis of osteosarcoma, while the MSC-derived osteoblasts deposit and mineralize the ECM." (PMID 37569894, 2023). "The results showed that there were significant negative correlations between the c-Myc expression level and those of CCL5, CXCL9, and CXCL10 in human osteosarcoma samples." (PMID 35292660, 2022). "In the present work, we first identified the relationship between c-Myc inhibition and upregulation of CCL5, CXCL9, and CXCL10 in osteosarcoma." (PMID 35292660, 2022). "MSCs, in turn, stimulate the migration of osteosarcoma cells by C-C motif chemokine ligand 5 (CCL5)/RANTES secretion, thereby favoring the spread of cancer by providing metastatic osteosarcoma cells with a favorable microenvironment." (PMID 33117154, 2020). "CCR5 receptor, that binds CCL3, CCL4, CCL5 and CCL8, is also involved in TAMs recruitment and plays a role in guiding invasion and metastasis of breast, cervical, lung, multiple myeloma, osteosarcoma, pancreatic, and prostate malignancies." (PMID 30591657, 2018). "Here we found a phenomenon whereby CCL5 and CCR5 interaction increased the migration and expression of αvβ3 integrin in human osteosarcoma cells." (PMID 22506069, 2012). "Our study presents that CCL5 and CCR5 interaction increases the expression of αvβ3 integrin via MEK, ERK, p65, and NF-κB-dependent pathway and increasing migration of human osteosarcoma cells." (PMID 22506069, 2012). "First, the expression of CCR1 that binds to 6 ligands (CCL3, CCL4, CCL5, CCL7, CCL16, CCL23) has been shown to correlate with metastases in lung, prostate, cervical and hepatocellular carcinoma, multiple myeloma, T-cell leukaemia, and osteosarcoma." (PMID 30591657, 2018). "Treatment of cells with cyclic RGD, but not cyclic RAD, inhibited the CCL5-induced migration of osteosarcoma." (PMID 22506069, 2012). "CCL5 and CCR5 interaction acts through MEK, ERK, which in turn activates NF-κB, resulting in the activations of αvβ3 integrin and contributing the migration of human osteosarcoma cells." (PMID 22506069, 2012). "On the other hand, we do not have clinical data to show the expression of CCL5 in osteosarcoma and healthy patients." (PMID 22506069, 2012). "No appreciable difference in cell growth ability was evident among these cells (data not shown), suggesting that CCL5 does not have any mitogenic effects in human osteosarcoma cells." (PMID 22506069, 2012). "Given that the expression of CCL5, CXCL9, and CXCL10 could be upregulated by a c-Myc inhibitor in the K7M2 model, we then asked whether this regulatory relationship also existed in human osteosarcoma." (PMID 35292660, 2022). "However, we found that high expression levels of CCL5 and CXCL10 were associated with improved survival in patients with osteosarcoma, although the association for CXCL10 was not considered statistically significant (p = 0.0597)." (PMID 35292660, 2022). "Therefore, CCL5 and CCR5 interaction is very important in migration activity of osteosarcoma cells." (PMID 22506069, 2012).
osteosarcoma (continued). "However, the effect of CCL5 and CCR receptor on integrins expression and migration activity in human osteosarcoma cells is mostly unknown." (PMID 22506069, 2012). "Furthermore, the two CD8 + cytotoxic clusters demonstrated upregulation of NKG7, GZMB, GZMH, GZMK, CCL3, CCL4, and CCL5, suggesting that chemotherapy amplified the cytotoxic function of CD8 + T cells, potentially enhancing their antitumor activity within the osteosarcoma tumor microenvironment." (PMID 39033089, 2024).
Anxiety (17 papers, 2016 to 2025). Intense feelings of nervousness, tension, or panic often arise in response to interpersonal stresses. "In summary, stress-induced upregulation of translation triggers CCL5 synthesis in CLNs and the onset of anxiety, although the underlying mechanism remains to be further investigated." (PMID 37903803, 2023). "Acute restraint stress induced anxiety-like behavior in rats, accompanied by a significant upregulation of Ccl5." (PMID 39905541, 2025). "Our findings revealed significant upregulation of chemokines Ccl3, Ccl4, Ccl5 and the inflammatory mediator Cd86 in Asm KO-induced anxiety." (PMID 39905541, 2025). "In mice with Autism spectrum disorder, gut microbiota transplantation treatment significantly ameliorated anxiety-like and repetitive behaviors and reduced levels of chemokines including Ccl3 and Ccl5." (PMID 39905541, 2025). "Chemogenetic inhibition of the projection from primary motor cortex to RN elicits anxiety-like behavior and CCL5 synthesis." (PMID 37903803, 2023). "Retrograde tracing from CLN identifies glutamatergic neurons in the red nucleus (RN), the activities of which are tightly correlated with CCL5 levels and anxiety-like behavior in male rats." (PMID 37903803, 2023). "The time spent in the central zone in the OFT and the open arm ratio in the EPM test were significantly increased in anti-CCL5 rats compared to IgG rats, suggesting that systemic neutralization of CCL5 reversed the anxiety induced by RN inhibition." (PMID 37903803, 2023). "Together, these loss-of-function experiments all support an essential role of the RN in anxiety-like behavior and CCL5 synthesis." (PMID 37903803, 2023). "The results of presynaptic and postsynaptic manipulation experiments indicate that the inhibition of the M1-RN pathway leads to anxiety-like behavior and CCL5 synthesis in CLNs." (PMID 37903803, 2023). "To test the functional impact of RN glutamatergic neuron activity on anxiety-like behavior and CCL5 synthesis, we stereotactically injected recombinant AAV conditionally expressing the inhibitory receptor hM4D(Gi)." (PMID 37903803, 2023). "In our study, inhibiting the M1-RN pathway induced anxiety-like behavior and CCL5 synthesis, demonstrating a pathway from the M1 directly to the RN for regulating anxiety-like behavior." (PMID 37903803, 2023). "Ablation or chemogenetic inhibition of RN glutamatergic neurons increases anxiety levels and CCL5 expression in the serum and CLNs, whereas pharmacogenetic activation of these neurons reduces anxiety levels and CCL5 synthesis after restraint stress exposure." (PMID 37903803, 2023). "The HADS-A score was lower in Q4 of CCL5 (p-value = 0.016) and anxiety was also less common in Q4 of CCL5 (p-value = 0.042)." (PMID 35504954, 2022). "In healthy hospital workers, anxiety scores were found inversely associated with levels of CCL2, CCL5, CCL11, and IL-6." (PMID 34863117, 2021). "Ileal Nfkb expression also coordinated with hippocampal Ccl5 and IL-6 production to predict anxiety-like behavior." (PMID 34248950, 2021). "The increase in CCL5 may be fed back to the brain through noradrenergic fibers, thereby affecting anxiety-like behavior." (PMID 37903803, 2023). "To further understand the role of CCL5 in RN inhibition-induced anxiety, we investigated whether systemic blockade of CCL5 influenced RN inhibition-induced anxiety using a specific neutralizing antibody." (PMID 37903803, 2023). "Taken together, these data suggested that the activation of RN glutamatergic neurons could attenuate restraint stress-induced anxiety-like behaviors and elevate CCL5 levels." (PMID 37903803, 2023). "The patients with anxiety (HADS-A ≥ 8) were less common in Q4 of CCL5 (p-value = 0.042)." (PMID 35504954, 2022). "A study on job stress outcomes reported lower serum CCL5 to correlate with higher anxiety scores." (PMID 36614020, 2022).
Anxiety (continued). "In this study, psychiatric symptom evaluations demonstrated that the Q4 of CCL5 had lower HADS-A scores and anxiety was less common in the Q4 of CCL5." (PMID 35504954, 2022). "Although acute restraint stress exposure increased CCL5 levels in both female and male rats, it failed to induce anxiety-like behaviors in female rats." (PMID 37903803, 2023). "Although female rats showed no anxiety-like behavior, we observed a sharp increase in CCL5 and corticosterone in both female and male rats on the first day of being subjected to restraint stress." (PMID 37903803, 2023). "Similarly, chemokines such as ENA-78/CCL5, GROα/CXCL1, MCP-1/CCL2, and TARC/CCL17 were increased in women displaying high anxiety levels." (PMID 34863117, 2021).
injury (17 papers, 2016 to 2025). Damage inflicted on the body as the direct or indirect result of an external force, with or without disruption of structural continuity. "MKC (murine KC, CXCL1), MCP-1 (CCL2) and RANTES (CCL5) are chemokines that are involved in the pathogenesis of acute lung injury." (PMID 38474386, 2024). "For example, CCR4 antagonist or modified CCL5 peptide reduced T cell and eosinophil infiltration and also attenuated AD-like skin injury." (PMID 32280674, 2020). "Platelet CXCL4 and CCL5 have been shown to be crucial involved in the recruitment and activation of neutrophils during the pathogenesis of acute lung injury." (PMID 30515177, 2018). "Although CCL5 administration showed some different activations of signaling molecules between WT and CCL5-KO, CCL5 makes a significant contribution to in vivo axonogenesis, synaptogenesis, and remyelination processes after brain injury in both WT and CCL-KO mice." (PMID 39285280, 2024). "Although the association between CCL2 and these two antioxidant-related genes is unknown, C-C motif chemokine ligand 5, a member of the same chemokine family, has been shown to enhance glutathione peroxidase 1 antioxidant activity in mice with mild traumatic brain injury." (PMID 36992978, 2023). "In addition, IL-1β, IL-6, TNFα, and the chemokines CCL5 and CXCL2 (which were all upregulated by LPA in primary microglia) are implicated as modulators of the neuroinflammatory response during traumatic brain injury where LPA levels are increased." (PMID 27565558, 2016). "In addition, platelet-derived chemokines like PF4 and CCL5 (RANTES) enhance neutrophil recruitment and activity, particularly under conditions such as acute lung injury." (PMID 40692784, 2025). "Furthermore, platelet CXCL4/CCL5 heterodimer binding to neutrophils has been shown to be necessary for neutrophil NET formation and release during the pathogenesis of acute lung injury." (PMID 30515177, 2018).
liver cancer (17 papers, 2013 to 2026). An epithelial or non-epithelial malignant neoplasm that arises from the liver. "We found that the ‘immune response’ genes enriched in the known liver cancer gene set and two known liver cancer genes (CCL5 and CXCL12) were associated with the enriched gene set (p < 10−4, Fisher's Exact Test)." (PMID 27220887, 2016). "It is known that CCL5 promotes tumour metastasis by inhibiting the ubiquitin degradation of HIF1α in human liver cancer, and that CCL5 expression is increased in human oesophageal cancer." (PMID 40500939, 2025). "In conclusion, our study suggests that the CCL5/CCR5/CYP1A1 pathway is activated during combination therapy to mediate metabolic reprogramming of liver cancer cells to resist lenvatinib." (PMID 39183447, 2024). "Sun and his team conducted single-cell sequencing of liver cancer CTCs and discovered that CCL5, regulated by the p38-MAX signaling pathway, was overexpressed in CTCs." (PMID 39227943, 2024). "Subsequently, we discovered the CCL5/CCR5/CYP1A1 pathway through RNA sequencing (RNA‐seq) on CCL5‐stimulated Huh7 cells and verified through a series of experiments that this pathway can mediate the resistance of liver cancer cells to lenvatinib." (PMID 39183447, 2024). "We found that CCL5 was the most prominent cytokine in the process of CAFs promoting liver cancer metastasis by cytokine antibody array." (PMID 35589690, 2022). "As a crucial regulator involving in the interaction between CAFs and liver cancer cells, CCL5 promotes HCC metastasis through activation of HIF1α/ZEB1 signaling axis." (PMID 35589690, 2022). "In this regard, C-C motif chemokine ligand 5 (CCL5) regulates ZEB1 in liver cancer." (PMID 41303618, 2025). "Additionally, in a rat primary liver cancer model, MSCs with high expression of SIRT1 (Ad-Sirt1-MSCs) promoted macrophage recruitment and synergistically facilitated liver cancer occurrence by secreting C–C chemokine ligand 5 (CCL5)." (PMID 37670393, 2023). "Moreover, we will further expand the clinic sample size to verify the function of CCL5 in liver cancer." (PMID 35589690, 2022). "With treatment of the Arf1 inhibitors, we observed increased CCL5 levels in the serum of mice bearing CT26 tumor and upregulated mRNA level of CCL5 in MYC-ON mouse liver cancer." (PMID 39872623, 2023). "In order to investigate the role of CCL5 during HCC progression, we collected three groups of clinical serum from liver cancer patients, liver cirrhosis patients and healthy person to detect CCL5 expression." (PMID 35589690, 2022). "CCL5 inhibited the ubiquitination degradation of HIF1α and up-regulated the downstream ZEB1 to promote liver cancer metastasis." (PMID 35589690, 2022). "Together with CCL7, CCL5 activates chemokine receptor 1 (CCR1), which was found to promote liver cancer by inducing myeloid cell infiltration and angiogenesis." (PMID 35585513, 2022). "In addition, CCL5 and HIF1α were positively correlated in clinical HCC samples, and high HIF1α expression was closely connection with poor prognosis in liver cancer patients." (PMID 35589690, 2022).
liver disease (17 papers, 2007 to 2026). "Similar results for CCL5 expression in hepatic tissue and serum suggest that serum CCL5 levels can indeed reflect the expression of CCL5 in hepatocytes during HBV-related liver disease progression." (PMID 31200663, 2019). "Multiple studies reported that CCL5 could recruit monocytes and be regulated by NF-κB; it played essential roles in liver disease progression, especially HCC development in humans and mice." (PMID 34795209, 2021). "CCL2 and CCL5 can recruit peripheral macrophages and T cells, a hallmark of ALF inflammation, and may play a central role in the pathogenesis of hepatic diseases, including ALF." (PMID 34877932, 2021). "Previous investigations indicated that CCL5 could mediate hepatic fibrogenesis in murine and human hepatic disease." (PMID 31200663, 2019). "As it is now well established that infiltrating immune cells play a pivotal role in both phenotypes of liver disease, these effects of [44AANA47]-CCL5 might be considered as the driving force behind the observed reduction of liver damage." (PMID 22574195, 2012). "Thus, the effects of [44AANA47]-CCL5 in our liver disease models appears to be mediated not only by quantitative effects of immune cell infiltration into the liver, but also by qualitative changes outside the liver." (PMID 22574195, 2012). "Furthermore, expression data and genetic analysis also suggest that CCL5 is involved in the pathogenesis of liver diseases in humans." (PMID 22574195, 2012). "Some of the PBMC proteins have been previously connected to liver disease including FSTL1, TSP1, CCL5, and TPM2." (PMID 38335183, 2024). "Moreover, during acute HCV infection, the increased expression of CCL5 is crucial for the induction of Th1 responses and the control of HCV infection and liver disease." (PMID 35632621, 2022). "The average serum CCL5 level of patients with HBV-related cirrhosis was significantly lower than that in CHB patients, it suggested that the serum level of CCL5 was an unfavorable marker of HBV-related liver disease progression." (PMID 31200663, 2019).
cervical cancer (16 papers, 2013 to 2025). A primary or metastatic malignant neoplasm involving the cervix. "Higher expression of downstream STING pathway genes (e.g., CCL5, CXCL10) is associated with better survival in cervical cancer patients." (PMID 40539072, 2025). "In cervical cancer, the CCL5 content was significantly increased in the primary tumor and also in metastatic lesions (lymph nodes or skin)." (PMID 34833360, 2021). "In a study investigating 23 cervical carcinomas, CCL5 levels were found to increase with advancing disease state." (PMID 34830895, 2021). "It is likely that SF-induced CCL2 and CCL5 can act in similar manner to enhance cervical cancer cell migration, invasion, and metastasis." (PMID 27446968, 2016). "CCL5, as a chemokine, shows expression correlation between immune cells and tumor cells in our data, suggesting it may play a key role in regulating the cervical cancer immune microenvironment." (PMID 40395456, 2025). "Notably, we uncovered a compelling association between CCL5, CXCL9, and CXCL10 and key prognostic factors, encompassing overall survival and progression-free survival, in cervical cancer, as observed within TCGA dataset." (PMID 38550593, 2024). "However, the role of CCL3 and CCL5 in cervical cancer needs to be further explored." (PMID 34830895, 2021). "SF regulated the expression of chemokines CCL2, CCL5, CXCL1, CXCL2, CXCL3, CXCL8 (IL-8), and CXCL11 all of which play vital role in cervical cancer inflammation and tumorigenesis." (PMID 27446968, 2016). "With this in mind, our subsequent investigation delves into the intricate correlation between the expression levels of STING downstream genes, CCL5, CXCL9, and CXCL10, and their influence on the overall immune infiltration status within the cervical cancer TME." (PMID 38550593, 2024).
tuberculosis (16 papers, 2008 to 2025). A chronic, recurrent infection caused by the bacterium Mycobacterium tuberculosis. "Genotypes or haplotypes associated with low CCL5 levels increased the susceptibility to severe enterovirus 71 infections and tuberculosis." (PMID 35632621, 2022). "Many case-control studies have been performed in the recent past to investigate the association between CCL5 -403 G>A (rs2107538) gene polymorphism and tuberculosis (TB) susceptibility in various ethnic groups." (PMID 24015211, 2013). "One recent paper assessing blood mononuclear cells from tuberculosis patients suggests that the polymorphism (TT genotype) of CCL5 may play an important role to decrease CCL5 expression in T cells to interfere immunity against tuberculosis." (PMID 28752079, 2017). "Combined with the results of other studies, CCL5 is likely to become a new target for the treatment of tuberculosis." (PMID 35345666, 2022). "Chemokine CCL5 was upregulated in all sentinels; CCL5 is detected in tuberculosis patients and important in the initial immune response after exposure to M. tuberculosis." (PMID 36051240, 2022). "The CC chemokine ligand 5 (CCL5), plays a key role in the inflammatory response by recruiting mononuclear cells during tuberculosis (TB) infection." (PMID 24376699, 2013). "Higher values of T-cell associated mediators (IL-4, -5, -7, -13, -17, -12p70; RANTES/CCL5, TNF-α) and growth factors (PDGF, FGF, and TGF-β1) grouped together in participants with a tuberculosis dissemination score of zero." (PMID 31276515, 2019).